POLR2J (RNA polymerase II subunit J)
Description:
Core component of RNA polymerase II (Pol II), a DNA-dependent RNA polymerase which synthesizes mRNA precursors and many functional non-coding RNAs using the four ribonucleoside triphosphates as substrates.
Synonyms: RPB11a; POLR2J1; RPB11; hRPB14; RPB11m
Tractability: Small molecule: a structure with a bound ligand is known. PROTAC: ubiquitination databases record sites on it; its protein half-life has been measured.
Gene: Protein-coding gene on chromosome 7 (102,473,128 to 102,478,929, reverse strand). Ensembl gene ENSG00000005075.
Subcellular location: Nucleus
Subcellular location (Human Protein Atlas): Nucleoplasm
Pathways (Reactome):
Disease: Abortive elongation of HIV-1 transcript in the absence of Tat; Dengue Virus-Host Interactions; Formation of HIV elongation complex in the absence of HIV Tat; Formation of HIV-1 elongation complex containing HIV-1 Tat; Formation of the HIV-1 Early Elongation Complex; HIV Transcription Initiation; HIV elongation arrest and recovery; Pausing and recovery of HIV elongation; Pausing and recovery of Tat-mediated HIV elongation; RNA Pol II CTD phosphorylation and interaction with CE during HIV infection; RNA Polymerase II HIV Promoter Escape; Signaling by FGFR2 IIIa TM; Tat-mediated HIV elongation arrest and recovery; Tat-mediated elongation of the HIV-1 transcript; Transcription of the HIV genome; Viral Messenger RNA Synthesis
Gene expression (Transcription): Formation of RNA Pol II elongation complex; Formation of the Early Elongation Complex; MicroRNA (miRNA) biogenesis; PIWI-interacting RNA (piRNA) biogenesis; RNA Pol II CTD phosphorylation and interaction with CE; RNA Polymerase II Pre-transcription Events; RNA Polymerase II Promoter Escape; RNA Polymerase II Transcription Elongation; RNA Polymerase II Transcription Initiation; RNA Polymerase II Transcription Initiation And Promoter Clearance; RNA Polymerase II Transcription Pre-Initiation And Promoter Opening; RNA polymerase II transcribes snRNA genes; Transcriptional regulation by small RNAs
Metabolism of RNA: Processing of Capped Intron-Containing Pre-mRNA; mRNA Capping; mRNA Polyadenylation; mRNA Splicing - Major Pathway; mRNA Splicing - Minor Pathway
DNA Repair: Dual incision in TC-NER; Formation of TC-NER Pre-Incision Complex; Gap-filling DNA repair synthesis and ligation in TC-NER; Transcription-Coupled Nucleotide Excision Repair (TC-NER)
Signal Transduction: Estrogen-dependent gene expression
and 3 more pathways
Gene Ontology:
Molecular function: LRR domain binding; protein binding; DNA-directed RNA polymerase activity; DNA binding; protein dimerization activity
Biological process: transcription by RNA polymerase II; transcription elongation by RNA polymerase II; transcription initiation at RNA polymerase II promoter; DNA-templated transcription
Cellular component: nucleus; RNA polymerase II, core complex; nucleoplasm
Genetic constraint (gnomAD): Loss-of-function variants: 12 observed, 8.97 expected, observed/expected ratio (o/e) 1.34, 90% interval 0.84 to 1.89. That is too few expected variants to judge how well the gene tolerates losing a copy. Missense variants: 53 observed, 93.3 expected, observed/expected ratio (o/e) 0.57, 90% interval 0.46 to 0.71. Synonymous variants: 29 observed, 37.7 expected, observed/expected ratio (o/e) 0.77, 90% interval 0.57 to 1.05.
Homologues: Orthologues: guinea pig Polr2j (100% identical), macaque POLR2J (100% identical), mouse Polr2j (100% identical), rat Polr2j (100% identical), zebrafish polr2j (95% identical), Drosophila melanogaster Polr2J (76% identical), Caenorhabditis elegans rpb-11 (67% identical). Paralogues in human: POLR2J3 (89% identical), POLR2J2 (88% identical), POLR1D (30% identical).
Diseases named in the same sentence as POLR2J in open-access papers:
POLR2J is named in the same sentence as 16 diseases in open-access papers, as found by Europe PMC text mining. Sharing a sentence is not in itself a finding about the gene and the disease. The quoted sentences say what the papers report.
rectal tumor (3 papers, 2020 to 2023). "We identified a group of genes of the biosynthetic machinery as rectal tumor organoid-specific, including those encoding the RNA polymerase II subunits POLR2H and POLR2J." (PMID 32824266, 2020). "We observed that POLR2H and POLR2J are exclusively overexpressed in rectal tumor organoids." (PMID 32824266, 2020). "Compared the gene profiling of organoids derived from a normal rectum and rectal tumors and their responses to calcitriol; Identified rectal tumor organoid-specific genes associated with biosynthetic machinery, including those encoding the RNA polymerase II subunits POLR2H and POLR2J." (PMID 35957894, 2022).
breast carcinoma (2 papers, 2013 to 2024). "Although functional studies have not directly implicated MAP2K1, POLR2J, and SEH1L in breast cancer development and progression, they have been associated with other malignancies." (PMID 38418940, 2024).
glioblastoma (2 papers, 2024 to 2025). The most malignant astrocytic tumor (WHO grade IV). "POLR2J expression is linked to the regulation of oxidative stress in glioblastoma cells." (PMID 41009025, 2025). "Silencing POLR2J significantly enhances the anti-glioblastoma activity of vorinostat, partly due to the suppression of cell proliferation and the induction of apoptosis influenced by oxidative stress levels." (PMID 41009025, 2025).
Huntington disease (2 papers, 2023 to 2024). Huntington disease (HD) is a rare neurodegenerative disorder of the central nervous system characterized by unwanted choreatic movements, behavioral and psychiatric disturbances and dementia. "Both TUBB4B POLR2J genes worked on Huntington's disease and RNA polymerase." (PMID 38957825, 2024).
COVID-19 (1 paper, 2024). A disease caused by infection with severe acute respiratory syndrome coronavirus 2. "Our comprehensive analysis revealed that four common genes, B4GALNT2, MTX1, POLR2J, and TUBB4B are differentially expressed in patients with both COVID-19 and diabetic peripheral neuropathy." (PMID 38957825, 2024).
Sepsis (1 paper, 2022). Sepsis is defined as life-threatening organ dysfunction caused by a dysregulated host response to infection. "Consistent with the trend observed in the hierarchical clustering analysis, the mRNA levels of seven featured genes in sepsis patients were significantly higher than those in the control group except for that of POLR2J." (PMID 35265105, 2022). "POLR2J and POLR2L are associated with purine metabolism and pyrimidine metabolism in sepsis patients." (PMID 35265105, 2022). "The results show that RNA expression levels of seven genes in sepsis were significantly higher than those in health, whereas one gene, POLR2J, showed an opposite trend in rats." (PMID 35265105, 2022). "In the present study, we also identified POLR2J and POLR2L as two of the hub genes of sepsis, indicating the important role of these two metabolism-related genes in the pathophysiology of sepsis." (PMID 35265105, 2022). "Meanwhile, the present study identified eight metabolism-related genes (NME1, NME6, POLD4, POLE4, POLR2J, POLR2L, ADCY3, and ENTPD1) in patients with sepsis and the identified metabolism-related genes may represent diagnostic and therapeutic biomarkers of sepsis." (PMID 35265105, 2022).
cancer (4 papers, 2015 to 2022). A tumor composed of atypical neoplastic, often pleomorphic cells that invade other tissues. "Genes containing AS events associated with overall survival are known components of cancer-related pathways, including regulation of transcription (E2F4, ZNF730, GPBP1, POLR2J, SP2, and CIART), cell cycle (E2F4 and GTSE1), or cell-cell adhesion (CEACAM1, MMP14, EPS8L2, AP3D1, AFDN, and PAK4)." (PMID 35044822, 2022).
tumor (4 papers, 2013 to 2025). "The expression levels of POLR2J and its co-expressed genes can predict outcomes in GBM patients, suggesting that oxidative stress, regulated by POLR2J, plays a significant role in the aggressiveness of the tumor and the overall prognosis for patients." (PMID 41009025, 2025). "POLR2J and its subtype POLR2J3 rarely appear in tumor studies, and it is even less reported in LSCC." (PMID 37598251, 2023). "The expression of many genes like TSC22D4, POLR2J, PPP1R, and C6ORF47 was dependent on the aggressiveness of the tumor." (PMID 27340651, 2013).
POLR2J also shares sentences with these, for which no sentence is quoted: colon tumor (1 paper); Immunodeficiency (1); leukemia (1); ovarian carcinoma (1); Parkinson disease (1); spinocerebellar ataxia (1); uveal melanoma (1); virus infection (1).